CSF1 (colony stimulating factor 1)
Diseases named in the same sentence as CSF1 in open-access papers (continued):
Sharing a sentence is not in itself a finding about the gene and the disease.
tumor (continued). "For example, CSF1 antibody, antisense oligonucleotide, and CSF1 small interfering RNA strategies have all demonstrated tumor suppression capabilities to various degrees in other disease and model systems." (PMID 20981142, 2010). "This appears to be regulated by oxygen tension, as several tumor cell lines cultured under hypoxic conditions downregulated CSF-1 gene expression." (PMID 19696929, 2009). "In support of these findings, hypoxic conditions down regulated CSF-1 production in several tumor cell lines and decreased RAW 264.7 macrophage migration in vitro." (PMID 19696929, 2009). "Together, the data presented here suggest a preliminary model where macrophages home to the tumor periphery during the early stages of tumor growth in response to CSF-1 released by normoxic tumor cells." (PMID 19696929, 2009). "Taken together, the data indicates that chemotaxis of RAW 264.7 macrophages to quiescent CT26 cells is robust and occurs primarily in response to tumor cell-secreted CSF-1, which can be further enhanced by exposure to macrophage-derived products." (PMID 19696929, 2009). "Together our findings suggest a model where normoxic tumor cells release CSF-1 to recruit macrophages to the tumor periphery where they secrete motility and angiogenic factors that facilitate tumor cell invasion and metastasis." (PMID 19696929, 2009). "Inflammatory gene array analysis and functional testing revealed that tumor cell-derived CSF-1 is the major chemoattractant for RAW 264.7 macrophages whereas macrophage derived SDF-1α and VEGF contribute to CT26 cancer cell invasion." (PMID 19696929, 2009). "Our findings indicate that there is a basal level of CSF-1 production by CT26 tumor cells that is sufficient to attract RAW 264.7 macrophages." (PMID 19696929, 2009). "This indicates the strong dependence of host CSF-1 level for efficient tumor cell seeding and growth in lung." (PMID 19668347, 2009). "While these studies clearly show that tumor derived CSF-1 can direct macrophage migration and infiltration into the tumor, several important questions remain." (PMID 19696929, 2009). "This conclusion was enhanced by the observations that treatment of mice that had been xenotransplanted with either a human colonic or embryonic tumour with antisense oligonucleotides directed against mouse CSF-1 reduced tumour growth and prolonged survival." (PMID 15164120, 2004). "Such tumour-produced molecules, including IL-4, IL-6, IL-10, CSF-1, TGFβ and prostaglandin E2 (PGE2), and TAM-produced factors such as IL-10 and PGE2, contribute to the general immunosuppression of the host as well as the antitumour activity of macrophages." (PMID 15164120, 2004). "Using genetic approaches, we demonstrated that depletion of CSF-1 in this model markedly decreased the infiltration of macrophages at the tumor site and this correlated with a significant delay of tumour progression to metastasis." (PMID 15164120, 2004). "In contrast, overexpression of CSF-1 in the tumour dramatically increased the macrophage density in the primary tumour and this was correlated with an accelerated malignant switch." (PMID 15164120, 2004). "However, the presence of a stiff ECM has been shown to enhance expression of CSF1 in breast cancer cells, facilitating the recruitment of tumor-promoting M2-like macrophages." (PMID 40453088, 2025). "Furthermore, M2-polarization of macrophages is promoted by growth factors, such as the colony-stimulating factor (CSF-1), and cytokines, like IL-4, IL-13 and IL-10, released by cells in the tumor-microenvironment." (PMID 39425000, 2025). "In addition, other genes activated by PPARδ, such as CSF1 (colony stimulating factor 1) and REG3G (regenerating islet-derived protein 3 gamma), encode secreted proteins that recruit myeloid-derived suppressor cells to the tumor microenvironment." (PMID 40247913, 2025).
tumor (continued). "In this model, we could isolate and block the tumor-derived CSF-1, as the tumor cells are the only human cells in the model and any CSF-1 produced by the mouse (e.g., macrophages, monocytes, endothelial cells, fibroblasts) is not inhibited." (PMID 40646332, 2025). "Additionally, tumor cells can secrete various cytokines and chemokines, such as CCL2 and CSF-1, which promote the migration of monocytes to the tumor site and facilitate their polarization into different types of TAM." (PMID 40370720, 2025). "Notably, tumor-specific intercellular signaling pathways, such as CSF1/CSF1R and CXCL/ACKR1, were identified, highlighting their potential role in fostering an immunosuppressive TME." (PMID 40438108, 2025). "Additionally, although the M1/M2 classification is widely employed in tumor-related research, particularly those investigating the CSF1/CSF1R axis." (PMID 40287444, 2025). "Furthermore, the use of anti‐CSF1/CSF1R agents has demonstrated synergistic effects with ADT in managing PCa by reducing pro‐tumor CAM infiltration both in vitro and in vivo." (PMID 40007149, 2025). "Tumor cells secrete cytokines, such as CSF-1, which bind to macrophage surface receptors and regulate the expression of immunosuppressive genes, including IL-1, IL-8, IL-10, and CSF-1." (PMID 40260303, 2025). "CSF1R expression is restricted to macrophages at the tumor site, indicating that CSF1 may promote metastatic potential by regulating the infiltration and function of TAMs." (PMID 40453088, 2025). "NHWD-870 has many beneficial properties, including inhibition of tumor proliferation by inhibiting BRD4 and c-MYC transcription, inhibition of tumor-associated macrophages (TAM) development, and reduction of CSF-1 (colony-stimulating factor) secretion by tumor cells." (PMID 40650308, 2025). "However, as tumours progress, the local cytokine milieu shifts to favour anti-inflammatory cues, such as IL-10 and CSF1, driving the recruitment of monocytes and their subsequent differentiation into immunosuppressive TAMs." (PMID 40948757, 2025). "We found that tumor cell-specific CSF-1 inhibition significantly increased VEGF-A levels in the TMEM doorway macrophage compared to control treated mice, consistent with the in vitro finding where CSF-1 signaling blockade prevented VEGF-A secretion from macrophages." (PMID 40646332, 2025). "Moreover, CSF-1 can recruit and reprogram TAMs to secrete factors that facilitate tumor growth and metastasis." (PMID 40079009, 2025). "This includes blocking “do not eat me” signals like CD47-SIRPα or CD24-Siglec-10 to enhance phagocytosis by macrophages, inhibiting monocyte recruitment or differentiation via pathways like CSF-1/CSF-1R, or attempting to repolarize M2-like TAMs towards an anti-tumor M1-like state." (PMID 40458806, 2025). "Tumour-derived CSF1 similarly drives RAE-1 expression on TAMs." (PMID 40948757, 2025). "CSF-1 immunoreactivity scores were calculated for each tumor component." (PMID 39488822, 2025). "Simulation results highlighted the correlation of CSF-1 concentration with tumor grade." (PMID 40845580, 2025). "Intermittent hypoxia activates the NF-κB/HIF-1α pathway, increasing pro-inflammatory mediators like COX-2, CCL2, CXCL1, PGE2, and CSF1, these mediators recruit monocytes and neutrophils to the tumor microenvironment (TME), differentiating into TAMs and Tumor-Associated Neutrophils (TAN)." (PMID 41357522, 2025). "Macrophages, particularly M2 macrophages, have a unique inhibitory role in the tumor microenvironment, and the colony-stimulating factor 1 (CSF-1) receptor (CSF-1R) plays a crucial role in the recruitment and differentiation of monocytes into pro-tumor M2 macrophages and their survival." (PMID 41247642, 2025). "Blocking the CSF1/CSF1R pathway suppresses macrophage migration into tumor tissue." (PMID 39941714, 2025).
tumor (continued). "Activation of genes related to this pathway (CSF2, SERPINE1, PDGFD, CYFIP2, IL7R, MYB, CSF1) can promote tumor cell proliferation and survival, and may also affect immune cells in the TME." (PMID 41328768, 2025). "CSF-1 binds to its receptor to recruit macrophages to tumor sites." (PMID 40547026, 2025). "Additionally, GF9 significantly decreases serum levels of macrophage colony-stimulating factor (M-CSF or CSF-1), a key factor promoting tumor growth and metastasis, indicating its potential anticancer properties via M-CSF suppression." (PMID 41226426, 2025). "Furthermore, in response to neuroblastic tumors cells, monocytes can differentiate into TAM, which can promote tumor cell invasion through a paracrine mechanism involving colony-stimulating factor 1 (CSF-1) and epidermal growth factor (EGF)." (PMID 40786507, 2025). "Additionally, colony-stimulating factor 1 (CSF1), plays a well-documented role in supporting the survival and proliferation of TAMs, thereby promoting tumor progression and suppressing anti-tumor immune responses 27-30." (PMID 40661379, 2025). "We thus hypothesize that hybrids may activate macrophages through CSF1, thereby promoting tumor growth in vivo." (PMID 40287444, 2025). "The use of CSF-1 monoclonal antibodies reversed macrophage aggregation and inhibited tumor growth." (PMID 40007537, 2025). "CSF-1 is a major survival factor for tumor infiltrating macrophages." (PMID 39055564, 2024). "However, the specificity and accuracy of artificial regulation of tumor systemic immunity are low (except for targeting colony-stimulating factor 1 (CSF-1))." (PMID 38816871, 2024). "Tumors, which are aberrant organs, secrete CSF-1 to recruit monocyte-derived macrophages as well as subvert the normal housekeeping activities of TRMs to promote tumor invasion and metastasis, angiogenesis, immunosuppression and resistance to cytotoxic therapies." (PMID 39588367, 2024). "In addition, CSF1 binding to CSF-1R activates the autocrine pathway of CSF-1, which endows the tumor with invasive and metastatic properties." (PMID 38303927, 2024). "Additionally, several immunosuppressive mediators, including CCL2, CCL5, CSF1, and TGFβ, secreted from CICs, are shown to promote macrophage and Treg recruitment into tumor tissue, while suppressing T cell responses, contributing to immune resistance." (PMID 38253555, 2024). "In addition, blocking the CSF1/CSF-1R axis can reduce the differentiation and recruitment of monocytes to tumor sites, thus further hampering the viability of existing TAMs." (PMID 39065562, 2024). "Since the presence of CSF1R+ macrophages within tumors correlates with poor survival in various tumor types, targeting CSF1/CSF1R signaling pathway transduction that promotes tumor growth is an attractive strategy to eliminate TAMs, reduce M2 macrophage recruitment, or repolarize them." (PMID 39416792, 2024). "Both IL-34 and CSF1, which are ligands for CSF1R, are known chemotactic factors for circulating monocytes secreted by SCs, and previous work has shown that both IL-34 and CSF1 are expressed in VSs, with a weak correlation between tumor growth and CSF1 levels described." (PMID 38216553, 2024). "Similarly, in MMTV neu transgenic mice, GW2580 (a specific CSF1 inhibitor) led to a considerable reduction in TAM infiltration in tumor tissue." (PMID 38273373, 2024). "Similarly, NPs coated with TAMm can drive M1 phenotype polarization by depleting macrophage colony-stimulating factors (e.g., CSF1) secreted by tumor cells, thereby reshaping the TME." (PMID 38675192, 2024). "CSF1 is the primary tumor-derived factor responsible for M2 recruitment." (PMID 38191673, 2024). "However, another relevant function of CSF1 is to promote M2-like polarization in tumors and to act as a chemotactic factor for M2-like TAMs in the tumor microenvironment." (PMID 38542388, 2024). "By binding to CSF-1R, CSF-1 produced by tumor cells promotes TAM recruitment and polarization." (PMID 39169402, 2024).
tumor (continued). "In addition to neutrophils, LY500307 inhibited the expression of CSF-1 in tumor cells, leading to reduced recruitment of myeloid-derived suppressor cells (MDSC) and an increase in CD8+ cytotoxic T cells in the tumor microenvironment." (PMID 39175529, 2024). "The CSF1 rearrangement is present only in 2–16% of tumor cells." (PMID 39459462, 2024). "The CSF1/CSF1R signaling pathway plays an important role in macrophage exhaustion, and its activation induces macrophage exhaustion, causing them to lose their anti-tumor function and instead support tumor growth and immune escape." (PMID 39416792, 2024). "Radiotherapy increases the release of CSF-1 from tumor cells and attracts macrophages to TME." (PMID 38474320, 2024). "The chemokines CSF-1 (also known as M-CSF), CSF-2 (also known as GM-CSF), and CSF-3 (also known as G-CSF) are also shown to be expressed by PCCs, leading to decreased concentrations of anti-tumor dendritic cells and increased concentrations of immune suppressive cells within the TME." (PMID 38361931, 2024). "This phenomenon may be attributed to the DNA damage, cell death, and heightened tumor hypoxia induced by the radiotherapy, leading to the upregulation of factors such as VEGF, SDF-1, and CSF-1, which in turn attract macrophages into the tumor environment." (PMID 38926205, 2024). "Tumor cells initiate recruitment of monocyte-derived circulating macrophages by production of Colony Stimulating Factor 1 (CSF1) and CC chemokine Ligand 2 (CCL2), leading to their binding to CSF1 receptor (CSF1R) and CCL2 receptor (CCR2) on the macrophage cell surface." (PMID 39660126, 2024). "Furthermore, they demonstrated that macrophage density correlated with ADT resistance and that macrophage depletion in mice (using a CSF1 antibody) reduced both tumor androgen levels and various surrogates of AR activation, as well as better outcome after ADT." (PMID 39635522, 2024). "Colony stimulating factor 1 (CSF1) signaling through its receptor, CSF1R, plays a pivotal role in the proliferation and differentiation of myeloid-derived suppressor cells (MDSCs) and M2-type tumor-associating macrophages (M2-TAMs)." (PMID 39201328, 2024). "One particular mechanism of therapeutic interference was revealed when paclitaxel treatment of PyMT mice was shown to increase tumor cell secretion of CSF-1 and IL-34 and addition of a CSF-1R inhibitor to the treatment regime reduced tumor growth and rates of pulmonary metastasis." (PMID 39588367, 2024). "TLR agonists have been identified as potent immunostimulatory molecules capable of inducing M1 macrophage repolarization, while the CSF1/CSF1-R signaling pathway between tumor cells and macrophages is responsible for the phenotypic transition to immunosuppressive M2 phenotype." (PMID 39175095, 2024). "In addition, CSF-1 can produce factors that promote tumor growth and metastasis by recruiting and reprogramming TAM." (PMID 39403370, 2024). "We differentiated primary human macrophages ex vivo using M-CSF (CSF-1), which may polarize toward an M2-like state and, therefore, may approximate macrophage polarization in the tumor microenvironment." (PMID 38483480, 2024). "Tumor-associated macrophages (TAMs) represent a major population within the immune cell component of the TME, recruited by various chemokines, including CCL2 and CCL5 and colony-stimulating factor 1 (CSF1)." (PMID 39877377, 2024). "Another study showed that the activation of YAP in tumor-initiating cells (TICs) recruits TIC-associated macrophages via the induction of C-C motif chemokine ligand 2 (CCL2) and colony-stimulating factor 1 (CSF1), suppressing the immune clearance of TICs to promote tumorigenesis." (PMID 38566194, 2024). "However, all microglia factor producing activity begins with CSF-1, a factor that is chemoattractant for microglia and is constitutively released by tumor cells." (PMID 38672638, 2024). "Tumor-derived signals include TGFβ, CSF1 and microRNAs delivered via exosomes." (PMID 39402303, 2024).
tumor (continued). "Based on signals received from tumor microenvironment, such as granulocyte-macrophage colony-stimulating factor (GM-CSF), colony-stimulating factor 1 (CSF1), IFN-γ, M0 macrophages polarize into two subtypes of tumor-associated macrophages (TAMs): anti-tumoral M1 and pro-tumoral M2-like TAMs." (PMID 39668828, 2024). "The accumulation of palmitic acid (PA), a long-chain saturated fatty acid, in Hep3B cells upregulates TGF-β1 expression and colony-stimulating factor 1 (CSF1), enhancing the polarization of M2 tumor-associated macrophages (TAMs) and the immunosuppressive phenotype of CAFs." (PMID 38891772, 2024). "Macrophages within the TME release proteolytic enzymes that breakdown the extracellular matrix and trigger a positive feedback loop consisting of tumor cell-produced CSF-1 and TAM-produced EGF promoting chemotactic migration of tumor cells toward blood vessels." (PMID 38533720, 2024). "Furthermore, transgenic expression of Csf-1 specifically in the mammary epithelium of Csf-1 null mice and wild-type (WT) mice accelerated tumor progression and lung metastasis." (PMID 37208442, 2023). "Inhibition of CSF1 reduces TAMs invasion as well as tumor proliferation and migration." (PMID 36941614, 2023). "BET inhibitors significantly inhibit CSF1 production by tumor cells, which could affect TAM-mediated cancer progression." (PMID 37926722, 2023). "Further characterization of our CSF1 knockout cell lines revealed several factors that could have contributed to the observed anti-tumor effect following vaccination." (PMID 37505292, 2023). "A previous study illustrated that crosstalk between tumor-promoting macrophages and the proximate vasculature creates a permissive niche for angiocrine-induced macrophage polarization driven by interleukin 6 (IL-6) and colony-stimulating factor 1 (CSF-1)." (PMID 37887354, 2023). "We next interrogated the impact of CSF1 deletion in the MC38 tumor microenvironment." (PMID 37505292, 2023). "The association of the macrophage population abundance with the disease prognosis dramatically depends on the tumor subtypes, so targeting the CSF1/CSF1R pathway may vary greatly depending on the tumor subtypes." (PMID 37279073, 2023). "Tumor cells secrete a plethora of chemokines, including colony-stimulating factor-1 and interleukins, to attract monocytes from the peripheral blood circulation into the tumor microenvironment (TME), ultimately inducing monocytes to differentiate into macrophages." (PMID 37469514, 2023). "On the other hand, the expression of the CSF1 gene in tumor cells could be demonstrated by RNA in‐situ hybridization (RNA scope) as coarse and fine granules." (PMID 37305870, 2023). "HIF-1α inhibits immune cells tumor killing function, which is mediated by regulatory cytokines, granulocyte macrophage colony-stimulating factor (GM-CSF), colony stimulating factor-1 (CSF-1), transforming growth factor-β (TGF-β), CC-chemokine ligand 5 (CCL5), and VEGF in TNBC." (PMID 37492478, 2023). "Tumor-derived CSF-1 promotes tumor growth and enhances M2 polarization and infiltration." (PMID 36816959, 2023). "Tumor cells secreted CSF1/M-CSF which acted as a chemoattractant for CSF1R+ MDSCs in vitro." (PMID 37686465, 2023). "Next, we evaluated the anti-tumor efficacy of CSF1 deletion in the MC38 tumor model." (PMID 37505292, 2023). "In addition, we evaluated the anti-tumor efficacy of combining CSF1 blockade with cancer vaccines in 4T1 and MC38 tumor models and further characterized its effect within the tumor microenvironment." (PMID 37505292, 2023). "Csf1, but not Csf2 or Il4, was highly expressed in tumors compared with tumor-distant liver tissues, implying that enhanced local production of M-CSF may stimulate KC mobilization and proliferation." (PMID 36821387, 2023). "Also, the tumor cells affect the macrophage cells by releasing the CSF-1 and increasing the macrophage recruitment and EGF secretion that facilitate the tumor cell's chemotaxis into the blood vessels." (PMID 38017494, 2023).